CD4 (CD4 molecule)
Diseases named in the same sentence as CD4 in open-access papers (continued):
Sharing a sentence is not in itself a finding about the gene and the disease.
tumor (continued). "The population of Tregs displaying a transcriptional fingerprint indicative of viral sensing and IFN signaling is less well defined in the literature, although very similar transcriptomic signatures have been observed in tumor-infiltrating CD4+ T cells." (PMID 34403374, 2021). "Using the co-culture system, Tr1 was generated from autologous CD4+CD25neg T cells by co-incubation with irradiated MDA-MB231 (CD73+) or MCF-7 (CD73neg) tumor cells and autologous iDC." (PMID 34442398, 2021). "Oral supplementation with A. muciniphila after FMT with non-responder feces restored the efficacy of PD-1 blockade in an interleukin-12-dependent manner by increasing the recruitment of CCR9+CXCR3+CD4+ T lymphocytes into mouse tumor beds." (PMID 34360566, 2021). "It has been shown that this expression significantly alters the tumor microenvironment by replacing a low population of tumor-infiltrating macrophages and neutrophils with activated CD4+ and CD8+ T-cells." (PMID 33499042, 2021). "In contrast, intratumoral injection of AAA-CD4+ T cells, which were produced from BALB/c mouse CD4+ T cells in B6 mouse-derived Flt3L-DCs pulsed with the tumor lysate elicited potent antitumor immunity against established B16F1." (PMID 34625113, 2021). "Date showed that in CD4+ T cells, naive CD4 and Treg cells in tumor expressed much more IL-32 than adjacent tissue, and in CD8+ T cell subsets, IL-32 expression was much higher in adjacent than tumor tissues." (PMID 34414188, 2021). "Expressing Foxp3 as key transcription factor, CD4+ Tregs are mainly recruited from blood and acquire Treg phenotype and function after entering tumor tissue, exerting a significant action on immunosuppressive TME." (PMID 34625124, 2021). "Human immunodeficiency virus (HIV) infects human dendritic cells and macrophages and activates CD4+ T lymphocytes, resulting in disruption of the immune system, so the tumor incidence and mortality differ from those in ordinary RCC patients." (PMID 34917092, 2021). "The VEGF inhibitor bevacizumab regulates a process called vessel normalization during angiogenesis through the upregulation tumor-infiltrating lymphocytes such as CD4+ and CD8+T cells in the TME." (PMID 33986746, 2021). "Yet TCR gene transfer therapy with CD4 tumor-specific TCRs is also limited by the challenging prediction and detection of MHC class II-restricted neoantigen-specific CD4 T cells, despite major advances." (PMID 34394096, 2021). "In tumor tissues, the increased numbers of CD4+ T cells/macrophages are observed with the increased expression of IL-2 and IL-12 and decreased expression of TGF-β." (PMID 33748122, 2021). "Enumeration of TAA-specific CD4 T cells is difficult, due to the low frequency of these cells in the circulation and at the tumor site." (PMID 34064410, 2021). "Therapeutic transfer of lung tumor-infiltrating activin-A-treated CD4+ T cells, delayed tumor progression in CD4−/− recipients and enhanced T cell-mediated immunity." (PMID 34548096, 2021). "Major components of the infiltrated immune populations are CD8+ and CD4+ T cells that can essentially contribute to tumor elimination." (PMID 34000441, 2021). "Depending of their polarization, CD4+ T cells are capable of either suppressing antitumoral immune responses or inducing tumor regression." (PMID 34335959, 2021). "The E. coli TOP10 is another such example that can induce significant tumor reduction in a colon carcinoma mouse model due to the induction of tumor-specific CD4+ and CD8+ T cells." (PMID 34138211, 2021). "Treatment with SPD alone significantly increased absolute counts of tumor-associated CD3 + and CD4 + cells compared to untreated controls (p < 0.05)." (PMID 34331595, 2021). "In 78% of the MCC patients, they detected specific CD4+ T-cells, which were highly enriched in the tumours." (PMID 34445385, 2021).
tumor (continued). "In the tumor tissues, naive B cells, activated and resting dendritic cells, M0 and M1 macrophages, activated and resting CD4 memory T cells and Tregs were mainly activated." (PMID 33289508, 2021). "This likely represents a distinct expression pattern for Tregs (shared by CD4_5 and CD4_7) compared to other tumor-infiltrating CD4+ T cells." (PMID 33504936, 2021). "The results from the C57BL/6 tumor samples showed that STAT3 targeting combined with PD-1 blockade leads to a high CD8/CD4 ratio and a decreased percentage of Treg cells." (PMID 33936081, 2021). "HLA class II, the human version of the major histocompatibility complex (MHC) class II, regulates the antitumoral cellular immune response by presenting MHC antigen in tumor cells to the immune system, stimulating tumor infiltration of CD4 + T cells." (PMID 33441805, 2021). "Treatment with the pan-PI3K inhibitor BKM120 in mice bearing breast tumors was found to increase the tumor infiltration of NK cells, B cells, and CD4 + and CD8 + T cells, favoring antitumor immunity." (PMID 33413549, 2021). "In line with previous studies on PD-L1 expression in cancer, we detected increased CD8+ and CD4+ T-cell densities in patients with high PD-L1 expression in tumor or immune cells of GBC." (PMID 33918309, 2021). "Recent evidence demonstrates that CD4+ TILs are capable of killing tumor cells and facilitating CD8+ TILs." (PMID 34900690, 2021). "Recently, it has become increasingly clear that CD4+ T cells play a critical role in developing and sustaining effective anti-tumour immunity, even in cancer immunotherapies specifically designed to activate a CD8+ CTL response." (PMID 32457487, 2021). "Further, isolation of tumor-specific CD4 T cells can be achieved based on the expression of activation markers, such as CD40L (CD154)." (PMID 34064410, 2021). "The expression of chemokines responsible for the attraction of CD4+ T cells at the tumor site can be modulated by epigenetics." (PMID 34262562, 2021). "Downregulation or indirect activation of MYC or N-MYC led to a repression of PD-L1 in the tumor and an influx of antitumor CD4+ T helper cells that correlated with tumor regression." (PMID 34299381, 2021). "Since primary CTLs (CD8+ T cells) responses are important in suppressing tumor growth and helper T cells (CD4+ T cells) play important roles in the regulation of adaptive immunity, they are considered critical effectors for cancer immunotherapy." (PMID 34362890, 2021). "Expression of iNOS in CD4+ T cells has also been reported to suppress Treg accumulation in pre-clinical cancer models and disrupt tumour tolerance by inhibiting production of TGF-β1." (PMID 33401460, 2021). "We have recently shown that ex vivo high-salt treatment of tumor-primed CD4 + T cells resulted in effector (Th1 and Th17) phenotype activation, and also exerted a strong anti-tumor effect." (PMID 34064273, 2021). "Lymphocytes, such as CD8+, CD4+ T cells, and natural killer (NK) cells, infiltrating the tumor is a prerequisite for a successful anti-tumor immune response." (PMID 33796460, 2021). "For example, CD4 + or CD8 + T cells are known to respond to new tumor antigens and react with cytokine release or antigen-specific cell killing." (PMID 34554502, 2021). "Understanding the impact of the tumor, through cytokines present in the microenvironment, but also the effect of anti-cancer therapies are critical aspects of immunotherapy research aiming at improving the anti-tumor response dependent on CD4 T lymphocytes." (PMID 33498483, 2021). "When given before or after tumor inoculation, α-GalCer co-formulated with tumor antigens increased overall survival in mice, a protective effect that was largely dependent on enhanced CD4 and CD8 T cell responses." (PMID 34680322, 2021). "MDSCs can inhibit the differentiation of tumor-specific CD4+ T cells into CD4+ Th1 cells through IL-6 production." (PMID 34681680, 2021).
tumor (continued). "Analysis of the effect of TEXomiR on the frequency of tumor-infiltrated CD4+CD25+Foxp3+ regulatory T cells was conducted by flow cytometry in a CD4+ T cell population." (PMID 33987190, 2021). "Both CD8+ and CD4+ T cells recognise tumour antigens; CD8+ T cells play the main role in the antitumour response and CD4+ T cells differentiate into several types of helper CD4+ T cells." (PMID 34680355, 2021). "Confocal images showed that tumor-infiltrating host CD8+ T cells were observed in more areas in the tumor from AAA-CD4+ T cell-treated mice than in auto-CD4+ T cell-treated mice." (PMID 34625113, 2021). "This is particularly true for CD4+ T cells and is noteworthy given increasing appreciation of the role of CD4+ T cells in tumour-specific immunity." (PMID 33662046, 2021). "Tumor derived PCs inhibit CD4+ T cell proliferation and activation while promoting CD4+ T cell anergy in vitro, which is also regulated by RGS5- and IL-6-dependent signaling pathways (process ➃)." (PMID 34179005, 2021). "Major targets include antigen-presenting DCs, CD8+ Teffector and CD4+ Thelper cell types, as well as regulatory Tregs, which are immunosuppressive and promote tumor growth and metastasis." (PMID 34503190, 2021). "Intraperitoneal injection of SR-8314 and SR-8291 led to increased frequencies of CD4+ and CD8+ T cells and a decrease in tumor-associated macrophages in tumor-bearing mice." (PMID 34070756, 2021). "An increased infiltration of activated CD44+CD3+CD4+ Th cells into the tumor and an increased IFNγ production were observed in this model." (PMID 34025657, 2021). "PD-L1 can block the cytolytic activity of PD-1+ tumor-infiltrating CD4+ and CD8+ T cells and cytokine production." (PMID 34728682, 2021). "E0771 tumor-bearing fat pad-infiltrating CD4 and CD8 T cells expressed elevated CD69, PD1, CTLA4, and CD25; with increased Tregs expressing inhibitory receptors PD1 and CTLA4." (PMID 33767151, 2021). "Previous studies revealed that the densities of specific tumor-infiltrating lymphocytes (TILs), such as CD8+ and CD4+ cells, were associated with cancer prognosis." (PMID 33747957, 2021). "The anti‐tumour cells including central memory CD4 T cell, central memory CD8 T cell, Th1 cell, Th17 cell, etc were higher in low‐level RAD51AP1 group; however, Th2 cell and the pro‐tumour cell were enriched in high‐level RAD51AP1 group." (PMID 33314567, 2021). "In support of the notion that antitumor immune response of KI mice is compromised, total numbers of tumor-infiltrating CD4+ and CD8+ T cells were reduced in KI>WT vs WT>WT mice." (PMID 33462142, 2021). "Although this function is usually attributed to CD8 T cells, tumor-reactive CD4 T cells can kill tumor cells expressing pMHC-II complexes, under certain conditions." (PMID 34201655, 2021). "Without the help of CD8+ T cells, transferring tumor antigen-specific CD4+ T cells induced tumor regressions in both mice and humans." (PMID 34885172, 2021). "As part of an anti-tumour immune response, infiltration by CD8+ and CD4+ T-cells results in recognition of tumour associated antigens presented on cancer cell surface using MHC-1 molecules, and a subsequent antitumour cytotoxic response." (PMID 33546207, 2021). "Infiltration of IFNγ-releasing CD8+ cytotoxic T cells and CD4+ helper T cells in the tumor environment was noticeably induced after rSmeg-hMIF-hIL-7 administration compared with Smeg administration." (PMID 34389619, 2021). "This interaction inhibits CD4+/CD8+ tumor-infiltrating T-lymphocytes (CD4+/CD8+ TILs), which results in a decrease in cytokines, such as Interleucin-2 (IL-2), interferon gamma (IFN-γ) and tumor necrosis factor (TNF)." (PMID 34943606, 2021). "For instance, Th1 activated with ICB plays a pivotal role in tumor vessel normalization, and ICIs-activated CD4+ T lymphocytes increases vessel normalization." (PMID 34692696, 2021).
tumor (continued). "In different tumor models, activation of the cGAS-STING signal pathway was found to be significantly associated with infiltration of macrophages, CD4+ T cells, CD8+ T cells, B cells, and dendritic cells, as well as their immune markers." (PMID 34956229, 2021). "Epigenetic modification plays an important role in the differentiation of CD4+ T cells, while the regulation of CD4+ T cells in anti-tumor activity still needs to be deeply explored." (PMID 33791306, 2021). "Splenic CD4+ T cells from tumor-bearing control (39 days after inoculation) or RFA-treated mice (21 days after treatment) were isolated and cultured in vitro." (PMID 34576115, 2021). "Consistent with previous findings 66, the GL261 GBM model showed a better response to PD-L1 blockade, reflected in significantly prolonged survival time, decreased tumor volume, and increased CD4+ and CD8+ T cells infiltration." (PMID 34815793, 2021). "In turn, a prominent population of regulatory CD4+ T cells (CD4+CD25+FOXP3+) infiltrating the tumor was detected." (PMID 34571910, 2021). "They show that citrullinated epitopes from ENO1 can be used in vaccines to induce potent CD4+ T cell responding to an anti-tumor effect with minimal cross reactivity to healthy tissue." (PMID 34671213, 2021). "Regulatory T cells (Tregs) are a group of CD4+ T cells with tumor-promoting effects, usually defined by the Foxp3+CD25+CD4+ T cell subpopulation." (PMID 34235155, 2021). "The positive effect of CD4+ tumor-infiltrating lymphocytes (TILs) on prognosis has been previously suggested for epithelioid, but remains controversial in sarcomatoid MPM." (PMID 34073720, 2021). "In adoptive cell transfer, the induction of CD4+ T cells persistence at tumor site represents a critical issue." (PMID 34262562, 2021). "PD-L1-containing exosomes have been involved in tumor progression in preclinical malignant glioma models; exosomal PD-L1 secreted by glioblastoma stem-like cells inhibited the activation of CD4+ and CD8+ immune effector cells." (PMID 34065396, 2021). "In the first series of experiments, miR-126 expression was shown to be nearly extinguished in tumor CD4+ T cells infected with GaHV-2." (PMID 34205549, 2021). "Currently, numerous studies have demonstrated that CD4+ T cells actively participate in shaping anti-tumor immunity." (PMID 33791306, 2021). "Although we had previously shown an increased tumor infiltration by CD4+ and CD8+cells in response to LFPRLR knockdown, those studies examined tumors at a later stage (42 days) when there were many fewer cells and large-scale necrosis." (PMID 34375938, 2021). "After i.t. co-stimulation with Ad-CD40L-DC, production of Th1-cytokines was strongly increased and accompanied by a robust tumor infiltration of mature DC, activated CD4+-, CD8+-T-cells as well as reduction of regulatory T-cells." (PMID 34282787, 2021). "Although DN subsets were predominant within CD4+ as well as CD8+ cells, a relevant fraction (comparable in frequency to Tregs) of these tumor-infiltrating CD4+ and CD8+ T cells exhibited the DP or SP phenotype." (PMID 34386013, 2021). "Conventional TREG can be attracted to the GC through CCL22 secretion, impairing T CD4+ or CD8+ activation by tumor antigens, with a pro-tumoral consequence." (PMID 33562694, 2021). "In this strategy, tumor specimens are used to provide tumor-infiltrating lymphocytes (TILs) containing CD8 and CD4 T cells, applying to recognize tumor-associated antigens and TCR sequences." (PMID 33654227, 2021). "In fact, in the CNS, the tumor cells are admixed with reactive CD4 and CD8 T cells and B lymphocytes, the functional role of which still remains to be defined." (PMID 34944954, 2021). "In murine tumor models, transient depletion of Treg cells led to activation of CD4+ or CD8+T cells and rejection of solid tumors." (PMID 33748292, 2021).
tumor (continued). "On the other hand, rich expression of IFN-γ, CXCL9, and CXCL10 and significantly high CTLA-4 or PD-1+ CD8/CD4 T cells were observed in the tumor microenvironment of CMS 1 patients." (PMID 33968712, 2021). "T cells CD4 memory activated, macrophages M0, and macrophages M1 were three immune cells increased in tumor tissues compared with normal tissues in both GEO and TCGA cohorts." (PMID 33442396, 2021). "The cold tumor with dominant CD4+ regulatory T-cells usually evades the immune system and dense desmoplastic TME hinders the access of therapeutic agents." (PMID 34638560, 2021). "To understand better the immunological processes in the treated tumors, we analyzed the tumor-infiltrating CD4+ and CD8+ T cells." (PMID 33408092, 2021). "Most immune cell subsets were seen to be represented in the tumor stroma, including CD4+ and CD8+ T cells, Tregs, B cells, macrophages, and NK cells." (PMID 34081628, 2021). "Hexatherapy treatment improved tumor growth control in primary and metastatic 4T1 settings compared with all the combinations tested by promoting effector CD4+ and CD8+ cells while at the same time limiting T cell exhaustion." (PMID 33602696, 2021). "Tumor-reactive CD4+ cells are adept at communicating with diverse innate and adaptive immune cell types within the TME." (PMID 33669271, 2021). "To further validate the activity of CD4+ T helper cells in tumor clearance, we also introduced CD4+ T cells into this tumor killing assay which further increased the tumor killing activity of CD8+ cells." (PMID 34906138, 2021). "MSCs, NLCs, follicular dendritic cells (FDCs) and follicular helper CD4+ cells (TFH) have been shown to exert their pro-tumor role through both contact-dependent and -independent mechanisms." (PMID 34445275, 2021). "CD4+TILs had an essential role in initiating anti-cancer immune responses that significantly affected the function of CD8+TILs against tumour cells." (PMID 35201470, 2021). "The results showed that there were more CAFs and macrophages in the tumor tissues than in the normal controls, while B cells, CD4+T cells, CD8+T, and endothelial cells were fewer than normal controls." (PMID 33588380, 2021). "In NSCLC patients, CD4+ T lymphocytes can be seen in tumor cells infiltrated by B cells and tumor cells with tertiary lymphoid structure." (PMID 34603645, 2021). "In this study, we show that CD4+ T cell exhaustion mediated by tumor cells results in a broad spectrum of transcriptomic changes." (PMID 34439305, 2021). "Tumor progression, tumor-infiltration by CD4+ and CD8+ T cells, and the development of TRP2-specific CD8+ T cells were then monitored over time." (PMID 33408093, 2021). "This anti-tumor response elicited by IL-36γ was characterized by increased production of IFN-γ by CD4+ cells, CD8+ cells, NK cells and γδ T cells, which ultimately resulted in the reduction of tumor size and higher survival." (PMID 34887860, 2021). "CD4+ T cells would acquire their ability to bind selectins in the tumor-draining lymph node as they engage cDC1 dendritic cells presenting tumor antigens." (PMID 33708224, 2021). "Another important feature in the tumor microenvironment is the presence of CD4+ T regulatory cells (Tregs)." (PMID 33924844, 2021). "Our studies testing another combination immunotherapy for CRC MSS highlight the influence of individual tumors on immune responses, as seen in distinct GrB+ TEM CD8+ versus CD4+TNFα+ driven responses to another tumor (CRC H,I)." (PMID 33854497, 2021). "The significant role of CD4 responses in tumour therapy is becoming clearer with several groups highlighting the importance of CD4 T cells in immunotherapy regimes." (PMID 34858415, 2021). "Ex vivo loading of primary cDC1s with tumor cell lysates induced CD8+ and CD4+ T-cell infiltration and reduced tumor progression in engrafted tumor models." (PMID 34262904, 2021). "For example, the opT cells from Pt38 were CD4 + cytotoxic T cells that killed tumor cells in a FasL dependent manner." (PMID 34789550, 2021).